CISD2 (CDGSH iron sulfur domain 2)
Diseases named in the same sentence as CISD2 in open-access papers (continued):
Sharing a sentence is not in itself a finding about the gene and the disease.
lung carcinoma (6 papers, 2017 to 2023). "CISD2 inhibits ROS production in lung cancer, which is reportedly associated with a poor prognosis of lung adenocarcinoma." (PMID 32009948, 2019). "The molecular mechanism underlying how CISD2 regulates ROS homeostasis and augments malignancy of lung cancer warrants further investigations." (PMID 28928421, 2017). "Despite these findings, it is still unclear whether CISD2 is associated with lung cancer." (PMID 28928421, 2017). "Subgroup analysis of CISD2 expression was performed in different clinical-pathological stages of lung cancer." (PMID 33598426, 2020). "We provide several lines of evidence to show that overexpression of CISD2 is oncogenic to lung cancer." (PMID 28928421, 2017). "We also examined CISD2 protein expression by Immunohistochemistry (IHC) assay using commercial lung cancer tissue microarrays." (PMID 28928421, 2017). "Our finding that CISD2 silencing-induced ROS can promote the expression of putative tumor suppressor EGR1 is also novel to lung cancer biology." (PMID 28928421, 2017). "Overall, we have defined a regulatory signaling pathway mediated by CISD2 in lung cancer that regulates the homeostasis of mitochondria and iron metabolism and may be developed as a novel pharmacological agent." (PMID 33598426, 2020). "The antioxidant but oncogenic roles of CISD2 in lung cancer are discussed." (PMID 28928421, 2017). "Upregulation of CISD2 in lung adenocarcinoma (ADC) specimens compared with their adjacent normal counterparts was found, and was associated with increased antioxidant capacity in response to elevated ROS levels during the formation and progression of lung cancer." (PMID 38155967, 2023). "Furthermore, CISD2 mediated ROS-EGR1-PTEN-AKT signaling causes EMT inhibition in lung cancer cells; however, the authors did not explain the underlying mechanism, although they did show that GPx3 overexpression inhibits cell growth." (PMID 30260967, 2018). "It would be worth investigating whether CISD2 also plays an oncogenic role in lung SQC and to explore its underlying mechanisms for identification of therapeutic targets in corresponding pathways for the effective treatment of lung cancers." (PMID 28928421, 2017). "CISD2, a member of the NEET family, can promote the invasion and migration of pancreatic cancer cells and promote the tumorigenesis and poor prognosis of lung cancer." (PMID 34485112, 2021). "In an initiative to scrutinize the roles of oxidative stress-related genes during tumorigenesis or progression of lung cancer, we noticed the upregulation of CISD2 (CDGSH iron sulfur domain 2) in lung adenocarcinoma (ADC)." (PMID 28928421, 2017).
head and neck cancer (5 papers, 2020 to 2024). A primary or metastatic malignant neoplasm affecting the head and neck. "Overexpression of CISD2 enhances the ability of head and neck cancer (HNC) cells to resist ferroptosis." (PMID 39605902, 2024). "Overexpression of CISD2 in head and neck cancer can enhance the resistance of sulfasalazine to ferroptosis." (PMID 34616431, 2021). "Regarding drug resistance, CISD2 has been identified as a novel biomarker of sulfasalazine resistance, and its inhibition promotes the sensitivity of head and neck cancer cells to sulfasalazine-induced ferroptosis by increasing the accumulation of iron oxide and lipid ROS in mitochondria." (PMID 34485112, 2021). "CISD2 inhibition overcomes resistance to SASP-induced ferroptosis through the increased accumulation of mitochondrial ferrous iron and lipid ROS in head and neck cancer." (PMID 33598426, 2020).
cervical cancer (4 papers, 2016 to 2023). A primary or metastatic malignant neoplasm involving the cervix. "Cervical cancer patients with higher CISD2 expression had shorter OS and were associated with pelvic lymph node metastasis." (PMID 38155967, 2023). "Upregulation of CISD2 is also found in early-stage cervical cancer and is linked to adverse prognosis." (PMID 35493303, 2022). "Recent studies have demonstrated CISD2 is elevated in human breast cancer and early-stage cervical cancer." (PMID 27007153, 2016).
fatty liver disease (4 papers, 2021 to 2022). A reversible condition wherein large vacuoles of triglyceride fat accumulate in liver cells via the process of steatosis. "Specifically, the development and progression of fatty liver toward NASH are accelerated by CISD2 haploinsufficiency, which leads to abnormalities in the ER and disturbances in intracellular Ca2+ homeostasis within hepatocytes." (PMID 36430496, 2022). "The development of therapeutic agents that effectively enhance Cisd2 expression is one potential approach to the treatment of WD-induced fatty liver diseases." (PMID 33916843, 2021). "The present study has also elucidated how Cisd2 acts as a protective mechanism against age‐related fatty liver and dysregulation of lipid metabolism." (PMID 34811857, 2021). "Taken together, these molecular events are all likely to contribute to the development of fatty liver disease and metabolic dysfunction when Cisd2 is down‐regulated." (PMID 34811857, 2021). "Development of therapeutic agents that are able to bring about an effective enhancement of expression of the Cisd2 might be a potentially therapeutic strategy for the treatment of fatty liver diseases induced by a Western diet." (PMID 33916843, 2021). "Using the upstream regulator analysis routine of the IPA program, we were able to predict that Cisd2 expression at a level similar to that found in young WT mice affected a number of upstream regulators and that these regulators play important roles in attenuating liver steatosis." (PMID 34811857, 2021). "Development of therapeutic agents that can bring about effective enhancement of expression of Cisd2 might have potential as a therapeutic strategy for the treatment of fatty liver diseases, thereby preventing subsequent malignant progression to cirrhosis and HCC." (PMID 34572415, 2021). "Altogether, our mouse studies show that CISD2 plays a pivotal role in protecting the liver from WD-induced NASH, and that CISD2 is a promising molecular target for the development of therapeutic agents for the treatment of WD-induced fatty liver diseases." (PMID 36430496, 2022).
lung adenocarcinoma (4 papers, 2017 to 2023). A carcinoma that arises from the lung and is characterized by the presence of malignant glandular epithelial cells. "Moreover, CISD2 expression is associated with a higher hazard ratio and exhibits significantly poorer overall survival in lung adenocarcinoma (LUAD), uveal melanoma, head and neck squamous cell carcinoma, brain lower grade glioma, kidney chromophobe, and liver hepatocellular carcinoma." (PMID 33598426, 2020).
pancreatic cancer (4 papers, 2021 to 2022). "In human pancreatic cancer, strong CISD2 expression showed a positive relationship with advanced vascular invasion, distant metastasis, clinical stage, T-stage, and larger tumor diameter." (PMID 35493303, 2022). "Moreover, CISD2 was shown to mediate longevity and to promote the development of breast cancer, cervical cancer, lung adenocarcinoma, pancreatic cancer, and prostate cancer." (PMID 34485112, 2021). "CISD2 may activate the WNT/β-catenin pathway and promote epithelial-mesenchymal transformation in pancreatic cancer." (PMID 35493303, 2022).
Alzheimer disease (3 papers, 2014 to 2024). A progressive, neurodegenerative disease characterized by loss of function and death of nerve cells in several areas of the brain leading to loss of cognitive function such as memory and language. "A higher level of CISD2 during natural aging, when achieved by transgenic overexpression, improves Alzheimer’s disease, ameliorates non-alcoholic fatty liver disease and steatohepatitis, and maintains corneal epithelial homeostasis." (PMID 36430496, 2022). "Additionally, CISD2 overexpression has demonstrated to have a protective effect against Alzheimer’s disease by reducing neuronal death and inflammation in the mouse hippocampus." (PMID 38263133, 2024).
Hearing impairment (3 papers, 2024 to 2025). A decreased magnitude of the sensory perception of sound. "Previous reports have also shown that WFS patients with Cisd2 deletion have severe hearing impairment and even hearing loss." (PMID 39226169, 2024). "In our previous studies, Cisd2 deficiency led to mitochondrial dysfunction resulting in neurodegeneration, which may induce hearing impairment." (PMID 39226169, 2024). "Cisd2 is a candidate gene for WFS2, and one critical impairment of WFS2 patients is hearing loss." (PMID 39226169, 2024).
peptic ulcer disease (3 papers, 2017 to 2021). A digestive system disease characterized by discontinuation in the inner lining of the gastrointestinal (GI) tract because of gastric acid secretion or pepsin. "Of note, all the patients with CISD2 mutations reported to date have developed peptic ulcer disease and a significant bleeding tendency, suggesting a possible genotype-phenotype association that is peculiar to WFS2." (PMID 28335035, 2017). "It seems that all patients with CISD2 mutation develop peptic ulcer disease and bleeding tendency." (PMID 33946243, 2021).
breast tumors (2 papers, 2023 to 2026). "Next, TCGA database indicated that all mRNAs encoding HO-1, CISD2, SOD-1 and GSR in breast tumors were significantly higher than those in normal tissues." (PMID 37217939, 2023).
Cirrhosis (2 papers, 2021). A chronic disorder of the liver in which liver tissue becomes scarred and is partially replaced by regenerative nodules and fibrotic tissue resulting in loss of liver function. "The upregulation of Cisd2 expression by a Cisd2 activator should be able to ameliorate intracellular oxidative stress, help maintain metabolic homeostasis, and bring about a reversal of steatosis, thereby preventing a subsequent malignant progression to cirrhosis and HCC." (PMID 33916843, 2021).
colorectal cancer (2 papers, 2023 to 2024). A primary or metastatic malignant neoplasm that affects the colon or rectum. "Increased CISD2 expression has been observed in colorectal cancer (CRC) cells, where it promotes CRC cell proliferation and inhibits both apoptosis and autophagy by activating the Wnt/β-Catenin signaling pathway." (PMID 39605902, 2024). "CISD2 infiltration of T cells in colorectal cancer samples exhibited a positive correlation with CISD2 levels." (PMID 37304867, 2023).
diffuse large B-cell lymphoma (2 papers, 2023 to 2024). "CDGSH iron-sulfur domain 2 (CISD2), an iron-sulfur protein with a [2Fe-2S] cluster, plays a pivotal role in the progression of various cancers, including Diffuse Large B-cell Lymphoma (DLBCL)." (PMID 39605902, 2024).
gastric tumor (2 papers, 2016 to 2017). "The percentage of gastric tumor tissues with a low level of CISD2 protein expression was much greater than that of the matched normal tissues (61.92% vs. 28.42%, P < 0.001)." (PMID 28857517, 2017). "Quantitative analysis revealed that the expression of CISD2 was significantly higher in the gastric tumors samples compared to the normal gastric tissue samples." (PMID 26565812, 2016). "Western blotting and real-time PCR analysis revealed that CISD2 protein and mRNA were both markedly overexpressed in the human primary gastric tumor tissues compared to the adjacent non-tumor gastric tissues." (PMID 26565812, 2016).
laryngeal squamous cell carcinoma (2 papers, 2016 to 2022). A squamous cell carcinoma that arises from the larynx. "The role of CDGSH iron sulfur domain 2 (CISD2) in laryngeal squamous cell carcinoma (LSCC) remains unclear." (PMID 27007153, 2016).
liver cancer (2 papers, 2021 to 2023). An epithelial or non-epithelial malignant neoplasm that arises from the liver. "However, CISD2 is infrequently reported in research of liver cancer." (PMID 34485112, 2021). "To understand the possible mechanism of CISD2, we conducted GSEA on database data for liver cancer samples." (PMID 34485112, 2021).
non-alcoholic fatty liver disease (2 papers, 2021 to 2022). "Furthermore, our previous studies revealed that CISD2 heterozygous knockout (CISD2+/−) mice were more susceptible to developing non-alcoholic fatty liver disease (NAFLD) and non-alcoholic steatohepatitis (NASH); these liver phenotypes are exacerbated during aging." (PMID 36430496, 2022).
Optic neuropathy (2 papers, 2014 to 2021). "A slowly progressive optic neuropathy, rather than OA can characterize patients with WFS2 and CISD2 intragenic deletion." (PMID 33996696, 2021).
autoimmune disease (1 paper, 2021). A disorder resulting from loss of function or tissue destruction of an organ or multiple organs, arising from humoral or cellular immune responses of the individual to their own tissue constituents. "Interestingly, the lead SNP at the MANBA/UBE2D3 locus, rs223486, is an intergenic variant located in a region (±500 kb) that harbors several other genes (CISD2, NFKB1, SLC9B1/2, BDH2 and CENPE) with reported inflammatory and autoimmune disease associations." (PMID 33402679, 2021).
autosomal dominant optic atrophy (1 paper, 2020). An autosomal dominant hereditary condition characterized by optic atrophy and progressive visual loss. "Mutations in OPA1 and MFN2 genes cause autosomal dominant optic atrophy (DOA); mutations in WFS1 and CISD2 can cause Wolfram syndrome, while Leber's hereditary optic neuropathy (LHON) is associated with mutations in mitochondrial ND1, ND4, and ND6 genes." (PMID 32352005, 2020).
bladder cancer (1 paper, 2025). "This study is the first to reveal the mechanism by which the Smad3/CISD2 signaling axis regulates ferroptosis in mesenchymal-like bladder cancer cells." (PMID 41413023, 2025). "Functional rescue experiments showed that CISD2 overexpression in Smad3-knockdown mesenchymal-like bladder cancer cells reversed abnormal increases in Fe2+, ROS, LPO, and MDA while restoring GSH levels, indicating that Smad3 modulates ferroptosis through a CISD2-dependent pathway." (PMID 41413023, 2025).
brain inflammation (1 paper, 2022). "Thus, spinal injury-induced brain inflammation decreases the expression of CISD2 and consequently contributes to the degeneration of the brain." (PMID 35453528, 2022).
brain tumor (1 paper, 2022). "The plasma and CSF levels of IL6 and CISD2 in 13 patients with CNS insult, including 11 head injury cases (6 TBI cases, 4 CVA cases, and 1 brain tumor case), 2 SCI cases (1 case each of AIS grade A [complete] and grade B [sensory incomplete] injuries), and 3 healthy controls were examined." (PMID 35453528, 2022).
colon cancer (1 paper, 2023). "This insinuates a strong immune response association for CISD2, potentially impeding colon cancer progression." (PMID 37304867, 2023). "In this investigation, CISD2 was determined to be essential for maintaining immune microenvironment homeostasis in colon cancer." (PMID 37304867, 2023). "Our analysis of CISD2 gene and copy number variation in colon cancer indicates that CISD2 significantly influences clinical prognosis and is more prone to undergo somatic copy number deletion." (PMID 37304867, 2023). "According to the relationship between CISD2 and immune cells, colon cancer patients with high CISD2 expression and CD8+ T cells experienced improved outcomes." (PMID 37304867, 2023). "By modulating the cell cycle and activating the immune system, CISD2 demonstrates statistical significance for prognosis in colon cancer." (PMID 37304867, 2023). "CISD2 expression levels reveal notable distinctions between high and low expression TCGA colon cancer samples, examined through comparative analysis." (PMID 37304867, 2023). "Through single-cell and single-gene analyses of colon cancer tumor samples, we identified a correlation between CISD2 and clinical outcomes, with elevated CISD2 expression conferring a protective effect against colon cancer and suppressing the immune system." (PMID 37304867, 2023). "The invasive propensity of colon cancer cells is curtailed by the augmentation of CISD2 expression." (PMID 37304867, 2023). "Consequently, CISD2 is considered a protective factor for colon cancer, exhibiting a robust immunological connection." (PMID 37304867, 2023). "In a pan-cancer analysis, CISD2 was highly expressed in most colon tumors (p < 0.001)." (PMID 37304867, 2023). "Assessing CISD2’s impact on colon cancer cell invasiveness, we conducted a wound healing assay." (PMID 37304867, 2023). "To explore CISD2’s potential role in colon cancer cell proliferation and carcinogenesis, we established HCT116 cell lines stably expressing CISD2." (PMID 37304867, 2023). "Conversely, low CISD2 expression displays increased KARS signaling DN, hedgehog signaling, myogenesis, and apical surface activation, suggesting interactions with colon cancer-related pathways." (PMID 37304867, 2023).
dementia (1 paper, 2020). Loss of intellectual abilities interfering with an individual's social and occupational functions. "Thus, CISD2 inactivity could be associated with the proinflammatory effects of M1 microglia underlying the pathological mechanism of neurodegenerative disease and dementia." (PMID 33005144, 2020).
developmental delay (1 paper, 2014). "Human genetic studies indicated that copy number variants (duplications and deletions) including CLN3, and possibly another gene in the CISD2/PPT1/CLN3 network, are over-represented in individuals with developmental delay." (PMID 24705017, 2014).
head and neck squamous cell carcinoma (1 paper, 2020). A squamous cell carcinoma that arises from any of the following anatomic sites: lip and oral cavity, nasal cavity, paranasal sinuses, pharynx, larynx, and salivary glands. "Further data indicated a significantly poorer OS in patients with high CISD2 expression in LUAD, uveal melanoma (UVM), head and neck squamous cell carcinoma (HNSC), brain lower grade glioma (LGG), kidney chromophobe (KICH), and liver hepatocellular carcinoma (LIHC)." (PMID 33598426, 2020).
Intellectual disability (1 paper, 2014). "We compared the frequencies of rare CNVs (deletions and duplications combined) encompassing CISD2, PPT1, CLN3 and their gene network partners in unaffected controls and in individuals with intellectual disability phenotypes." (PMID 24705017, 2014).
intracerebral hemorrhage (1 paper, 2025). A cerebrovascular disorder characterized by bleeding into one or both cerebral hemispheres including the basal ganglia and the cerebral cortex. "For example, CISD2 protects neurons after intracerebral hemorrhage by inhibiting ferroptosis through the AKT/mTOR pathway." (PMID 41261172, 2025).
iron deficiency (1 paper, 2021). "The much higher stability of CISD2 under conditions of iron deficiency might be understood as resulting from a stronger binding of the Fe–S cluster to the protein, from a greater stability of the apoprotein in cells, or from both of these possibilities." (PMID 33916457, 2021).
liver fibrosis (1 paper, 2021). "Remarkably, in the WD-fed Cisd2TG mice after 4 months, the two-fold overexpression of Cisd2 could be seen to have obviously brought about a decrease in lipid droplet deposition, while at the same time there had been a discernible attenuation of liver inflammation and reduced liver fibrosis." (PMID 33916843, 2021).
low grade glioma (1 paper, 2022). A grade I or grade II glioma arising from the central nervous system. "The results from the ssGSEA and TIMER databases confirmed that CISD2 acts a prominent role in immune cell infiltration in the tumor microenvironment, especially in low-grade glioma (LGG)." (PMID 35493303, 2022).
lymph node metastasis (1 paper, 2016). "CISD2 was significantly correlated with T stage, lymph node metastasis, clinical stage and disease progression." (PMID 27007153, 2016). "Moreover, the MOD values of CISD2 staining were markedly higher in the lymph node metastasis group than that in the lymph node metastasis free group (P < 0.001)." (PMID 27007153, 2016).